PPARG (peroxisome proliferator activated receptor gamma)
Diseases named in the same sentence as PPARG in open-access papers (continued):
Sharing a sentence is not in itself a finding about the gene and the disease.
breast cancer (continued). "Hence, the attenuated PPARγ signaling in LATS2-depleted breast cancer cells may account, at least in part, for the observed increase in glycolysis and the increased dependence on glucose for survival." (PMID 30456386, 2018). "Whether VDR, RXR or PPARγ are expressed in BRCA1 mutated breast cancer or may even be present in case of triple negativity is not known." (PMID 28427429, 2017). "Thus, the majority of aggressive breast cancers would be expected to be responsive to a PPARδ agonist or PPARγ antagonist that could reverse the negative regulation by PPARγ on the ER+ lineage." (PMID 28881566, 2017). "As VDR, RXR and PPARγ can be quantified in cancer tissue easily, they - given them being present in BRCA1 mutated breast cancer cases at all - may evolve as novel alternative biomarkers, especially for hormone receptor negative or even triple negative breast cancer patients." (PMID 28427429, 2017). "The peroxisome proliferator-activated receptor-gamma was found to have important roles in the development and progression of breast cancer, and the peroxisome proliferator-activated receptor-gamma ligands have been found to reduce migration and invasion of breast cancer cells." (PMID 27625789, 2016). "However, despite these studies, either the regulatory mechanism by which PPARγ may regulate CXCR4 expression in breast cancer cells or how PPARγ works in the context of breast tumor microenvironment remain largely unknown." (PMID 27556298, 2016). "Peroxisome Proliferator-Activated Receptor gamma (PPARγ), a ligand-activated transcription factor belonging to the nuclear hormone receptor superfamily, apart from the well-established adipogenic and metabolic actions, has evolved to a breast cancer tumor suppressor." (PMID 27556298, 2016). "Collectively, our findings provide novel insights into the role of PPARγ in inhibiting breast cancer progression and further highlight the utility of PPARγ ligands for future therapies aimed at targeting both cancer and surrounding stromal cells in breast cancer patients." (PMID 27556298, 2016). "Interestingly, in the present study, treatment with ROSI caused induction of BRCA1 expression in PPARγ-WT, but not PPARγ-MG KO mouse mammary tumours." (PMID 25889730, 2015). "In light of the increased expression of PPARγ in breast cancer cell lines and its association with acidic intracellular pH, we hypothesized that, in addition to inhibiting NHE1 activity, ligand-induced activation of PPARγ could regulate NHE1 gene expression." (PMID 23431283, 2013). "In addition, PPARγ reduces levels of survivin in different cancer types, including breast cancer." (PMID 24034496, 2013). "Taken together these results suggest that breast cancer cells require PPARγ activation for their survival, and that treatments designed to reduce or inhibition of PPARγ levels and/or activation and may provide an effective strategy in treatment of breast cancer." (PMID 23431460, 2013). "However, the inhibitory effect of PPARγ on breast cancer cells was weakened in the midterm stage." (PMID 24137293, 2013). "Previous studies have suggested that PPARγ activation results in extensive accumulation of lipids and changes in mammary epithelial cell gene expression that promotes a more differentiated and less malignant phenotype, and attenuates breast cancer cell growth and progression." (PMID 23431460, 2013). "However, activation of PPARγ by 15d-PGJ2 upregulates VEGF expression in human breast cancer cells via induction of heme oxygenase-1 and phosphorylation of ERK1/2, which may contribute to increased angiogenesis of the tumor cells." (PMID 22934105, 2012). "In light of previous reports that Heregulin plays a causal role in Tamoxifen- and Gefitinib-resistant breast cancer, Park's work provides evidence that combination therapy with Heregulin and PPARγ-activators may be a novel strategy for the treatment of resistant or refractory breast cancer." (PMID 22966225, 2012).
breast cancer (continued). "Thus, tocopherols may indirectly activate PPARγ, and possibly through this pathway may interfere with ERα expression, inhibit cell cycle progression and induce apoptosis to prevent breast cancer." (PMID 22254089, 2011). "Possible mechanism of actions in inhibiting breast cancer could be: inducing PPARγ expression and as a result reducing the expression of ERα, inducing Nrf2 which consequently reduces inflammation and oxidative stress, and inhibiting cell proliferation while inducing apoptosis." (PMID 22254089, 2011). "In addition to controlling the expression of many genes involved in lipid metabolism, and insulin sensitization, it has been found that PPARγ functions as a tumor suppressor in a variety of malignancies such as breast cancer, colon cancer, liposarcoma, ovarian cancer, and prostate cancer." (PMID 20650001, 2010). "Previous studies suggested that PPARg signalling may exacerbate mammary gland tumour development in mice and PPARg ligands have been shown to inhibit the proliferation and induce the apoptosis of breast cancer cell lines in vitro through the activation of PPARg." (PMID 22276018, 2009). "Interestingly, tumor breast tissue expresses PPARγ in amounts greater than normal breast epithelium, suggesting for a novel therapeutic approach for ligand-activated PPARγ as an anti-tumor agent in differentiation-based breast cancer therapy." (PMID 19958503, 2009). "Also, overexpression of the Bag1 gene in mammary carcinomas may limit the efficacy of PPARγ agonists, like 15-deoxy-PGJ2, as apoptosis-inducing agents." (PMID 19399228, 2009). "Thirty-eight women with early stage breast cancer were treated withRosi for 2–6 weeks withtumor growth inhibition or progression as an end point.The data indicate that short-term Rosi therapy in early-stage breast cancerpatients has both local and systemic effects on PPARγ signaling." (PMID 19096712, 2008). "PPARγ is known to be expressed in avariety of cancer, and the treatment of these cancer cells with PPARγ ligands often induces celldifferentiation and apoptosis, andexerts antiproliferative effects on human colon cancer,breast cancer,pituitary adenomas,gastric cancer, and bladder cancer." (PMID 18483618, 2008). "Whether PPARγ agonists manifest similar interactions with 4HPR in breast cancer cells is unknown." (PMID 15505623, 2004). "PPARG plays a crucial role in determining the efficacy and prognosis of HER2-positive breast cancer." (PMID 40303293, 2025). "At the same time, we divided HER2-positive breast cancer patients in our center and METABRIC database into PPARG-low and PPARG-high expression groups based on median PPARG expression levels in tumor tissue." (PMID 40303293, 2025). "This research identified the key gene PPARG, which plays a role in promoting resistance in HER2-positive breast cancer, through the construction of resistant cell lines and screening of public databases." (PMID 40303293, 2025). "In turn, upon PPARG gene knockout, HER2-positive breast cancer cells showed enhanced sensitivity to anti-HER2 drugs." (PMID 40303293, 2025). "We analyzed RNA‐seq data from primary breast cancer patients in the TCGA‐BRCA cohort, stratifying patients by PPARγ expression, menopausal status, and tumor receptor subtype." (PMID 41236441, 2025). "Among these pathways, the p-ERK and p-AKT signaling in breast cancer, the LRP6/GSK3β/β-catenin axis in NPC, and the cytosolic fatty-acid-binding protein 7 (FABP7)/PPARγ axis in malignant gliomas have been reported." (PMID 40001923, 2025). "We hypothesize that PPARγ expression and adipose proliferation differentially affect survival across subtypes and menopausal status, providing deeper insight into PPARγ as a therapeutic target in breast cancer and the potential implications for precision medicine treatments." (PMID 41236441, 2025). "Following PPARG overexpression, HER2-positive breast cancer cells showed reduced sensitivity to trastuzumab, pyrotinib, and lapatinib." (PMID 40303293, 2025).
breast cancer (continued). "Epigenetic de-repression transforms PPARG into a drug target for TNBC and endocrine-resistant breast cancer." (PMID 40604951, 2025). "The basal and luminal subtypes of bladder cancer share molecular features with basal and luminal breast cancers, including the TP63 activation in the basal tumors and overexpression of PPARG in the luminal tumors." (PMID 40605119, 2025). "In this study, we investigated KA’s role in regulating PPARγ activity and its anti-inflammatory and anticancer effects mediated by NOX4-induced ER stress signaling pathways and apoptosis in breast cancer." (PMID 39770941, 2024). "MMPP promoted apoptosis in breast cancer cells via cleavage of caspase-3, caspase-8, and caspase-9 and regulation of Bcl-2 and Bax through the VEGFR2/AKT and PPARγ/PTEN/AKT pathways." (PMID 37942548, 2024). "However, the effect of dual-targeting drugs for VEGFR2 and PPARγ in breast cancer remains unclear." (PMID 37942548, 2024). "Using a combination of PPARγ agonists and MEK inhibitors, we forced the differentiation of disseminating breast cancer cells into post-mitotic adipocytes." (PMID 39273076, 2024). "MAPK/ERK is a signaling pathway from membrane receptors to the nucleus, and PPARγ activated by ROSI will inhibit phosphorylation of ERK, thereby inhibiting the growth of melanoma and breast cancer cells." (PMID 37251321, 2023). "In summary, the PPARγ and CaMKII axis mediated by FABP5 plays a crucial role in breast cancer chemoresistance." (PMID 37538178, 2023). "For example, it downregulates ERK1/2 through PPARγ in MCF-7 breast cancer cells, and inhibits the Akt/GSK-3β survival pathway by activating PTEN in SKBR3 and T47D breast cancer cell lines." (PMID 37511450, 2023). "In another in vivo study in a rat model of breast cancer, direct upregulation of PTPRF gene expression by PPARγ had some inhibitory effect on tumor cell proliferation." (PMID 37251321, 2023). "In summary, we propose that six key compounds, luteolin, apigenin, quercetin, kaempferol, ursolic acid, and oleanolic acid, contributed to the development of breast cancer by affecting the MMP9 and PPARG proteins." (PMID 37180727, 2023). "In studies suggesting that PPARg has tumour-promoting effects, T0070907 has been proven to inhibit the formation of ERBB2-positive breast cancer cells into tumours, the growth of hepatocellular carcinoma cells and the brain metastasis of melanoma." (PMID 36681687, 2023). "Breast cancer cells secrete WNT proteins and exosomes to inhibit the expression of PPARγ in adjacent adipocytes to form CAAs, and CAAs obtain a malignant phenotype in the TME compared with normal adipocytes." (PMID 36765683, 2023). "A study in 2009 reported that breast cancer cells positive for ERBB2 (an epidermal growth factor receptor, a marker of poor prognosis) produce large amounts of fat due to the activation of PPARγ, a key pathway for these cells to produce energy and survive." (PMID 37251321, 2023). "To answer this question, we cocultured patient-derived breast cancer organoids, PDM92 and PDM250, with either control pericytes (GFP+, low PPARγ expression) or PPARγ-overexpressing pericytes (PPARγ-OE)." (PMID 37816052, 2023). "All-trans retinoic acid, an endogenous retinoid, has been shown to inhibit the expression of PPARγ and to enhance the expression of DOK1 as it regulates the DOK1/PPARγ pathways thus inhibiting cell proliferation in breast cancer (MCF7 cell line)." (PMID 38274206, 2023). "Having previously demonstrated that ethanolamide derivative DHEA modulates PPARγ expression and activity in MCF-7 breast cancer cells, we investigated the involvement of this receptor in the effects of DHEA on TNBC cells." (PMID 36765778, 2023).
breast cancer (continued). "Increased glycolysis and L-lactic acid secretion in CAFs overexpressing PPARγ was also observed, while the growth rate of MDAMD-231 breast cancer cells was significantly accelerated by the implantation of such CAFs." (PMID 37251321, 2023). "PPARγ and ERα physically interacted to regulate the PI3K/AKT signaling pathway, which is involved in breast cancer cell survival and proliferation." (PMID 36611922, 2022). "Subsequently, 10 top hub genes were identified and five (IGF1, ADIPOQ, PPARG, LEP, and NR3C1) significantly correlated with worse OS and BCSS on response to trastuzumab in breast cancer patients." (PMID 35317079, 2022). "Clinical studies have identified PPARγ expression as a positive prognostic factor in ductal breast cancer and higher concentrations of PPARγ seem to correlate inversely with grading, size and TNM stage of breast cancer." (PMID 35079875, 2022). "Oncoprint analysis showed genetic alterations in FABP4 (14%), ADIPOQ (2.9%), PPARG (2.8%), PPARGC1A (1.5%), CD36 (1.7%), and CREBBP (11%) in patients with breast cancer in a TCGA study." (PMID 36114448, 2022). "This study explored the potential targets of RGZ as antiangiogenic agents in breast cancer therapy and highlighted FABP4, ADIPOQ, PPARG, PPARGC1A, CD36, and CREBBP as potential targets of RGZ." (PMID 36114448, 2022). "We have found that NSAIDs, as PPARγ agonists, activate PRODH/POX-induced ROS-dependent apoptosis in breast cancer MCF7 cells." (PMID 35163433, 2022). "The mammary secretory-epithelial-cell-specific knockout of PPARγ enhanced tumor growth in a 7,12-dimethylbenz[a]anthracene (DMBA)-induced breast cancer model." (PMID 35954274, 2022). "In MCF-7 breast cancer cells, curcumin activated AMPK as an upstream signal of PPARγ in 3T3-L1 adipocytes, resulting in the down-regulation of PPARγ and a decrease in differentiation of adipocytes." (PMID 36092543, 2022). "The potent, irreversible and selective PPARγ antagonist GW9662 was proved to prevent the activation of PPARγ and inhibit growth of human mammary tumor cell lines." (PMID 35842709, 2022). "We demonstrated a heatmap and prognostic value of DNA methylation clustering of the expression levels of FABP4, ADIPOQ, PPARG, PPARGC1A, CD36, and CREBBP in breast cancer." (PMID 36114448, 2022). "Oncoprint analysis revealed genetic alterations in FABP4 (14%), ADIPOQ (2.9%), PPARG (2.8%), PPARGC1A (1.5%), CD36 (1.7%), and CREBBP (11%) in patients with breast cancer in a TCGA study." (PMID 36114448, 2022). "Patients with breast cancer who had low mRNA levels of FABP4, ADIPOQ, PPARG, and PPARGC1A had lower overall survival rates than those with high mRNA levels, which was supported by the overall survival related to DNA methylation." (PMID 36114448, 2022). "NR4A1 has been found to bind to the NBRE or coactivator SWI/SNF complex response elements by NR4A2 or PPARγ, resulting in the change of fatty acid-related genes ACOX, CPT1M, FABP2, and FABP4 in melanoma and breast cancer." (PMID 36052242, 2022). "DNA methylation analysis revealed that the predictive significance of FABP4, ADIPOQ, PPARG, PPARGC1A, CD36, and CREBBP in a specific CpG was significant in the emergence of breast cancer." (PMID 36114448, 2022). "The activation of PPARγ by 15d-PGJ2 has also been demonstrated to inhibit tyrosine phosphorylation of epidermal growth factor receptors ErbB-2 and ErbB-3 in a breast cancer cell line, leading to a dramatic increase in apoptosis." (PMID 35954274, 2022). "PTER-ITC revealed anticancer potential on breast cancer cell lines (MCF-7 and MDA-MB-231) through activation of PPARγ, PPARβ,p38 MAPK, JNK, caspase 9, caspase 7, and caspase 3 pathways and downregulation of Bcl-2 and survivin." (PMID 36092543, 2022).
breast cancer (continued). "Patients with breast cancer who had low mRNA expression levels of FABP4 (log-rank P = 0.012), ADIPOQ (log-rank P = 0.01), and PPARG (log-rank P = 0.00013) had worse OS than those with high mRNA levels." (PMID 36114448, 2022). "Oncoprint analysis revealed genetic alterations in FABP4 (14%), ADIPOQ (2.9%), PPARG (2.8%), PPARGC1A (1.5%), CD36 (1.7%), and CREBBP (11%) in patients with breast cancer in the TCGA study." (PMID 36114448, 2022). "As conjugates of DHA and EPA, DHEA and EPEA elicit anticancer effects by PPARγ-mediated autophagy, while DHADA and EPADA triggered intrinsic apoptosis after long term treatment through PPARγ involvement in breast cancer cells." (PMID 34444715, 2021). "Stimulation of PPARγ by pioglitazone can downregulate P450 aromatase expression through the induction of BRCA1 and through the inhibition of the PGE2/cAMP/KA pathway in breast cancer." (PMID 34204039, 2021). "Our first step was to deconvolute the clinicopathological and molecular correlates of PPARγ and HDAC expression in breast cancer." (PMID 34580286, 2021). "We previously showed that pharmacologic inhibition of PPARγ by GW9662 boosts αPD-L1 and αPD-1 antibody efficacy in treating murine mammary tumors." (PMID 32226299, 2020). "Interestingly, the antiproliferative effects of PPARγ ligands are stronger in TNBC cells compared to ERα-positive breast cancer cells, addressing that PPARγ agonists could be a good therapeutic tool for the management of the more aggressive breast cancer subtypes." (PMID 32937951, 2020). "PPARG is therefore plausibly involved in the development of DA, NDA, and PD, as well as breast cancer." (PMID 33037222, 2020). "Thus, PPARγ agonists may represent potential agents for the BCSC-target therapy in breast cancer." (PMID 33352766, 2020). "Moreover, mature muscle cells co-cultivated with breast cancer cells underwent cell death, myosin heavy chain 1 loss, myotube atrophy, increased UCP3 levels, overexpressed P-p38 and downregulated P-ERK1/2, PPARG and P-PPARG when compared with muscle cells cultivated alone." (PMID 32325796, 2020). "In this context, the aim of the present review is to summarize PPARγ activity in breast TME focusing on the role of this receptor on both epithelial/stromal cells and extracellular matrix components of the breast cancer microenvironment." (PMID 33352766, 2020). "Previous study also indicated that the tumor suppressor and anti-inflammatory actions of PPARγ agonists were mediated via upregulation of PTEN in Caco2 colorectal cancer cells and MCF7 breast cancer cells." (PMID 30845932, 2019). "Our results show that PPARγ agonist suppresses the NF-κB DNA-binding activity and blocks E2-induced apoptosis in LTED breast cancer cells." (PMID 31815253, 2019). "However, neither VDR nor RXR nor PPARγ have been studied in BRCA1 associated breast cancer so far." (PMID 28427429, 2017). "For instance, knockdown of BRCA2 in breast cancer cell lines modulated expression of RXR isoforms in opposing ways and knockout of BRCA1 reduced expression of PPARγ in cardiomyocytes." (PMID 28427429, 2017). "In this context, PPARγ activation by GW501516 increased arachidonic and linoleic acids in mammary tumors, and elicited an inflammatory gene signature in other animal models, which are also consistent with PPARδ-mediated repression of PPARγ." (PMID 28881566, 2017). "The results from breast cancer confirmed those from metastatic melanoma, indicating FAK regulates E-cadherin expression via p-SrcY416/ p-ERK1/2/p-Stat3Y705 and PPARγ/miR-125b/Stat3 signaling pathway." (PMID 28108732, 2017).